TXNRD1 (thioredoxin reductase 1)
Diseases named in the same sentence as TXNRD1 in open-access papers (continued):
Sharing a sentence is not in itself a finding about the gene and the disease.
myocardial infarction (3 papers, 2018 to 2025). Gross necrosis of the myocardium, as a result of interruption of the blood supply to the area, as in coronary thrombosis. "In the treatment of myocardial infarction, we have obtained key targets of Yixinyin, which are ALDH2, C5AR1, FOS, IL1B, TLR2, TXNRD1." (PMID 34799616, 2021).
Sepsis (3 papers, 2016 to 2025). Sepsis is defined as life-threatening organ dysfunction caused by a dysregulated host response to infection. "Inhibiting TXNRD1 maintains TXN in its oxidized state, restricting Caspase-11 activation and alleviating sepsis." (PMID 39744566, 2025). "The boxplot revealed 26 differentially expressed genes between the sepsis-induced ALI and control samples: Ncf2, Slc2a6, Cd44, Txnip, Slc2a1, Ubc, Hspb1, Zfp36, Arntl, Ddit4, Tnfaip3, Txnrd1, Mt1, Hmox1, Gch1, Gclc, Stat3, Egfr, Hif1a, Bach1, Socs1, Dusp1, Cdkn1a, Fth1, Steap3, and Alox12." (PMID 37081490, 2023).
Tremor (3 papers, 2008 to 2019). An unintentional, oscillating to-and-fro muscle movement about a joint axis. "Already at P7, Txnrd1-NS null mice showed ataxic gait, impaired balance, and tremor." (PMID 18350150, 2008).
type I diabetes (3 papers, 2021 to 2023). "(rhizome), berberine promoted wound healing in both type I diabetes and type II diabetes, which decreased oxidative damage, cell apoptosis, and ECM remodeling through thioredoxin reductase 1/c-Jun N-terminal kinase (TrxR1/JNK) signaling." (PMID 35069970, 2022).
viral infection (3 papers, 2016 to 2025). "To assess whether this impaired expansion in Txnrd1-deficient T cells arose from defective in vivo cycling or increased cell death, we next measured cell proliferation during the course of a viral infection by incorporation of EdU." (PMID 29749372, 2018).
acute liver failure (2 papers, 2021 to 2024). Rapid deterioration of liver function causing encephalopathy and coagulopathy. "In APAP-induced acute liver failure patients (GSE74000), IKBKG levels decreased, and Nrf2 target genes were also repressed (i.e., HMOX1, PRDX1, TXNRD1, GPX4, GPX1, GCLC, GCLM, and NQO1)." (PMID 38505605, 2024).
adenoma (2 papers, 2018 to 2025). A neoplasm arising from the epithelium. "The only significant findings for adenomas were negative correlations for the SELENOP levels with TXNRD1 disease (p = 0.006) and SELENOW normal (p = 0.042) tissue expressions." (PMID 30469315, 2018).
atherosclerosis (2 papers, 2017 to 2025). A disease characterized by the build-up of fatty material and calcium deposition in the arterial wall resulting in partial or complete occlusion of the arterial lumen. "Of particular interest, pathway enrichment analysis of the 34 common gene associated DMRs revealed epigenetic impairment of NRF2 oxidative stress (SOD2), DNA repair (BRCA1), thioredoxin (TXNRD1) and inflammatory pathways (MIF, PLA2G4D) in atherosclerosis conditions." (PMID 28698603, 2017).
Cognitive impairment (2 papers, 2019 to 2023). Abnormal cognition is characterized by deficits in thinking, reasoning, or remembering. "Taken together, the results seem to demonstrate that disruption of the homeostasis of one-carbon metabolism induces altered DNA methylation patterns of NUDT15 and TXNRD1 and thus leads to oxidative stress overload and increased susceptibility to cognitive impairment." (PMID 31601260, 2019).
diffuse large B-cell lymphoma (2 papers, 2022 to 2025). "Our data are consistent with a recent report, in which GPX4 and TXNRD1 were still expressed in diffuse large B-cell lymphoma cell lines apparently deficient in SECISBP2 immunostaining, although it was not further studied what kind of mutations may have caused the lack of SECISBP2 protein." (PMID 36291713, 2022). "Co-targeting of BTK and TXNRD1 is an effective therapeutic strategy to consider for Diffuse large B-cell lymphoma (DLBCL) treatment." (PMID 39744566, 2025).
Hyperglycemia (2 papers, 2013 to 2023). An increased concentration of glucose in the blood. "Interestingly in contrast to HUVEC, the gene expression of ROS clearance enzymes, SOD1, GPX1, TXNRD1, TXNRD2, and PRDX1 were upregulated in HMVEC under hyperglycemia." (PMID 24093550, 2013). "Not much detail is available in literature for hyperglycemia-induced gene expression of NFE2L2, TXNRD1, TXNRD2 and PRDX1 in HUVEC." (PMID 24093550, 2013). "Taken together, these findings in tissue-specific cells show that hyperglycemia converges on major insulin, lipid, and fibrosis pathways by DNA methylation to regulate the expression of core genes that consist of but are unlikely to be limited to MTOR, RPTOR, IRS2, TXNRD1, LCAT, SMPD3, and COL1A2." (PMID 36633903, 2023).
hypertrophy (2 papers, 2019 to 2021). Hypertrophy is the increase in the volume of an organ or tissue due to the enlargement of its component cells. "Cardiac hypertrophy in response to triiodothyronine or isoproterenol treatment was found to upregulate the expression of MsrB1, GPX3, GPx4, and Txnrd1, leading to the speculation that their increased expression may mitigate cardiac damage following induction of hypertrophy." (PMID 34579115, 2021).
invasive breast carcinoma (2 papers, 2015 to 2023). A carcinoma that infiltrates the breast parenchyma. "MCM2 and TXNRD1 were underexpressed (p < 0.05) in DCIS patient samples but not in invasive breast cancer samples." (PMID 37445737, 2023).
lung disease (2 papers, 2021 to 2022). "In summary, clinical Se deficiency must be corrected for the optimal therapeutic effectiveness of TXNRD1 inhibitors in the prevention of lung disease." (PMID 36570123, 2022).
Obesity (2 papers, 2013 to 2022). Accumulation of substantial excess body fat. "Molecular pathway analysis of LRRK2 reveals direct links between LRRK2 and the thioredoxin system, which interacts with PRDX3, TXNIP and TXNRD1, proteins that are associated with nutrient sensing, adiposity and human obesity." (PMID 23799078, 2013).
Parkinson disease (2 papers, 2022 to 2023). A progressive degenerative disorder of the central nervous system characterized by loss of dopamine producing neurons in the substantia nigra and the presence of Lewy bodies in the substantia nigra and locus coeruleus. "Reduced mRNA expression of Txnrd1 is associated with Parkinson’s disease, which has a pathology similar to CICI due to oxidative stress." (PMID 35216124, 2022).
rectal cancer (2 papers, 2012 to 2019). A primary or metastatic malignant neoplasm that affects the rectum. "In these data TXNRD1, TXNRD2, TNXRD3, SepX1, and SelN1, and SeP15 also were associated with survival after diagnosis with colon or rectal cancer." (PMID 22615972, 2012). "In this paper we evaluate associations between genetic polymorphism in TXNRD1, TXNRD2, TXNRD3, C11orf31 (i.e. SelH), SelW, SelN1, SelS, SepX, and SeP15 and colon and rectal cancer." (PMID 22615972, 2012). "Associations between TXNRD1, TXDRD2, TXNRD3, SelN1, and SepX1 and colon and rectal cancer." (PMID 22615972, 2012).
triple-negative breast carcinoma (2 papers, 2021 to 2022). An invasive breast carcinoma which is negative for expression of estrogen receptor (ER), progesterone receptor (PR), and human epidermal growth factor receptor 2 (HER2). "Silencing TXNRD1 was proven to enhance cytotoxicity of triple-negative breast cancer cells." (PMID 34395526, 2021).
acute lung injury (1 paper, 2020). A condition of lung damage that is characterized by bilateral pulmonary infiltrates (pulmonary edema) rich in neutrophils, and in the absence of clinical heart failure. "Thioredoxin reductase-1 (TXNRD1) inhibition activates nuclear factor (erythroid-derived 2)-like 2 (Nrf2) responses and prevents acute lung injury (ALI)." (PMID 32587658, 2020).
asthma (1 paper, 2026). "Multi-omics integration associated ALAS1 (cg13241645, cg15698299) and TXNRD1 (cg09884423) with asthma at both methylation and expression levels, with colocalization supporting both ALAS1 associations." (PMID 41896191, 2026). "This study provides multi-omics evidence supporting a causal role for mitochondrial-related genes, particularly ALAS1 and TXNRD1, in paediatric asthma, offering new insights into pathogenesis and potential therapeutic targets." (PMID 41896191, 2026).
autoimmune type 1 diabetes (1 paper, 2018). Autoimmune disease wherein the body's own immune system attacks and destroys the cells within the pancreas that produce insulin. "NOD mice, which are a polygenic model for autoimmune type 1 diabetes, had lower expression of Dio1 and Txnrd1 relative to other strains; Se deficiency, however, resulted in increased expression of Dio1 and Txnrd1 relative to the other strains in NOD mice." (PMID 29338053, 2018).
brain cancer (1 paper, 2024). A primary or metastatic malignant neoplasm affecting the brain. "We subsequently utilized the Correlation AnalyzeR web application to generate a scatter plot analysis of GCLC and Txnrd1 co-expression in normal and brain cancer tissue." (PMID 39456455, 2024). "We identified a significant increase in GCLC and Txnrd1 co-expression in brain cancer tissue (Pearson R = 0.44, padj = 1.28 × 10−5) compared to normal brain tissue (Pearson R = 0.25, padj = 3.41 × 10−5)." (PMID 39456455, 2024).
brain tumors (1 paper, 2022). "To broaden the knowledge about the expression of TrxR1 in brain tumors, we ana-lyzed the publicly available datasets for the gene expression of TXNRD1 mRNA in GBM and NT brain tissues." (PMID 36555352, 2022).
bronchopulmonary dysplasia (1 paper, 2019). Bronchopulmonary dysplasia is a chronic respiratory disease that results from complications related to lung injury during the treatment of infant acute respiratory distress syndrome in low-birth-weight premature infants or from abnormal lung development in older infants. "Aurothioglucose- (ATG-) mediated inhibition of thioredoxin reductase-1 (TXNRD1) improves alveolarization in experimental murine bronchopulmonary dysplasia (BPD)." (PMID 30805084, 2019).
colorectal adenoma (1 paper, 2012). An adenoma that arises from the colon or rectum. "Others have shown significant associations between TXNRD1 rs35009941 and colorectal adenomas." (PMID 22615972, 2012).
depression (1 paper, 2024). "Our data revealed that MGO-induced depression like-behavior and memory deficits resulted from disturbances in Trp, 5-HT, BDNF, and NGF levels, increased p-Tau and APP expression, neuroinflammation, and impaired redox status (Nrf-2/Ho-1/TXNRD1/Sirt3/5) in the brain." (PMID 39574138, 2024).
ductal carcinoma (1 paper, 2011). "Mcs6 human orthologous transcripts that have been reported as differentially expressed between non-diseased breast tissue and ductal carcinoma tissue encode for two phosphatases (DUSP6, PPP1R12A), a proteoglycan (EPYC), a redox regulator (TXNRD1), and two uncharacterized proteins (ALX1, ZDHHC17)." (PMID 21625632, 2011).
duodenal ulcer (1 paper, 2014). An ulcer in the duodenal wall. "Our invivo data confirm that DSW ingestion attenuates the area of acetic acid-induced duodenal ulcers and apoptosis numbers via the action of selenium to induce Bcl-2 and Txnrd1 expression." (PMID 24984066, 2014).
emphysema (1 paper, 2009). "In C57BL6/J mice, intra peritoneal injection of recombinant human Txnrd1 or in human Txnrd1 transgenic mice resulted in a reduction in cigarette smoke-induced lung inflammation and emphysema." (PMID 19698101, 2009).
endometriosis (1 paper, 2020). The growth of functional endometrial tissue in anatomic sites outside the uterine body. "In an attempt to answer this question, this study compared the genetic variants of three different oxidative stress enzymes (GPX4, TXN2 and TXNRD1) and evaluated if there is a difference in genotype and allele frequency between women with endometriosis and healthy controls." (PMID 32679649, 2020). "In this study, we compared the genetic variation of three antioxidant enzymes, GPX4, TXN2 and TXNRD1 and attempted to identify whether there is any difference in allele frequency between endometriosis and control patients." (PMID 32679649, 2020). "In order to further explore the role of the thioredoxin system and its impact on endometriosis, we chose to analyze SNP (rs1128446) of TXNRD1 gene, located on chromosome 12." (PMID 32679649, 2020). "No significant risk of endometriosis by genotype was found in the TXNRD1 (rs1128446) through this study." (PMID 32679649, 2020). "Because the C:G allele of TXNRD1 (rs1128446) is 179:1 in patients with endometriosis, the comparison between stage of the disease is not practical for biostatistics." (PMID 32679649, 2020). "This prospective case-control study attempted to check the connection between single nucleotide polymorphism (SNP) of three antioxidant enzymes (glutathione peroxidase 4 (GPX4), thioredoxin 2 (TXN2), thioredoxin reductase 1 (TXNRD1)) and endometriosis." (PMID 32679649, 2020). "This study focused on a SNP of the TXN2 gene (rs4821494) and a SNP of the TXNRD1 (rs1128446), both have been reported to be overexpressed by cancer cells, but currently no strong evidence in relation to endometriosis." (PMID 32679649, 2020).
genetic generalized epilepsy (1 paper, 2017). A generalized epilepsy that is understood to have a genetic etiology. "Kudin and colleagues report a mutation in thioredoxin reductase 1 (TXNRD1) and its association with genetic generalized epilepsy." (PMID 29117123, 2017).
gout (1 paper, 2019). A condition characterized by painful swelling of the joints, which is caused by deposition of urate crystals. "There was increased expression of TXNRD1 in the monocytes from gout patients, but no change in expression of SOD2 or of TAC." (PMID 30761138, 2019).
hemochromatosis (1 paper, 2023). A disorder of iron metabolism characterized by a triad of HEMOSIDEROSIS; LIVER CIRRHOSIS; and DIABETES MELLITUS. "Treatment with the potent but promiscuous TXNRD1 inhibitor, auranofin, in a hemochromatosis mouse model showed an increase in hepatic malondialdehyde (MDA), a product of lipid peroxidation, and Ptgs2 mRNA levels, which is highly associated with ferroptosis." (PMID 37087975, 2023).
HIV-1 infection (1 paper, 2022). The type species of lentivirus and the etiologic agent of acquired immunodeficiency syndrome (AIDS). "Based on the migration on SDS-PAGE and radioactive signal intensity, it was suggested that TXNRD1, GPX4 and GPX1 were downregulated in Jurkat cells after HIV-1 infection in favor of one or more low-molecular-weight selenocompounds." (PMID 35163318, 2022). "We monitored the expression of five selenoproteins, namely GPX4, GPX1, SELENOO, TXNRD1 and SELENOS, in response to HIV-1 infection at various time points and in cellular protein extracts." (PMID 35163318, 2022).
Insulin resistance (1 paper, 2016). Increased resistance towards insulin, that is, diminished effectiveness of insulin in reducing blood glucose levels. "Our observations that TXNRD1 transcript levels inversely associate with clinical signs of human insulin resistance in vivo and in adipocytes in vitro warrant further studies addressing the potential role of TrxR1 as a therapeutic target in diseases affecting glucose and/or lipid metabolism." (PMID 27346647, 2016).
liver cirrhosis (1 paper, 2022). "However, high TXNRD1 expression was positively associated with liver cirrhosis (P = 0.028)." (PMID 36319631, 2022).
liver disease (1 paper, 2023). "When the liver is impaired in alcohol metabolism, gene expression in the liver (such as Txnrd1, Txnrd3, Txn1, and Txn2) decreases significantly, indicating the risk of liver disease and the need for timely intervention." (PMID 36765968, 2023).
lung carcinoids (1 paper, 2019). "Despite all these considerations, the KEAP1 silencing studies support the hypothesis that KEAP1 acts in lung carcinoids by modulating the levels of NRF2 and the NRF2-detoxification enzymes TXNRD1 and NQO1." (PMID 31126053, 2019).
malaria (1 paper, 2023). Malaria is a serious and sometimes fatal disease caused by a parasite that commonly infects a certain type of mosquito which feeds on humans. "In a translational approach, seizures are a common symptom of severe malaria, suggesting that the TXNRD1 gene may be involved in seizures associated with severe malaria." (PMID 37048057, 2023).
metastatic cancers (1 paper, 2015). A carcinoma which has spread from the original site of growth to another anatomic site. "In addition, increased expressions of TXN and TXNRD1 were correlated with clinical stage and distant metastasis in SACC patients, which supports previous report that TXN overexpression is an independent prognostic factor in metastatic cancers." (PMID 26325518, 2015).
pancreatic ductal adenocarcinoma (1 paper, 2019). An infiltrating adenocarcinoma that arises from the epithelial cells of the pancreas. "We hypothesize that auranofin may prevent pancreatic ductal adenocarcinoma progression by inhibition of Txnrd1 and HIF-1α." (PMID 33981979, 2019).
parasite infection (1 paper, 2018). "However, Txnrd1 is critical for expansion of the activated T-cell population during viral and parasite infection." (PMID 29749372, 2018).
periodontitis (1 paper, 2025). An acute or chronic inflammatory process that affects the tissues that surround and support the teeth. "Moreover, TXNRD1 has emerged as a promising prognostic marker for T2DM risk, particularly in familial forms of the disease, while GCLC (p < 0.01) and GCLM as well as HMOX1 (both p < 0.05) appear to play a role under specific clinical conditions of periodontitis accompanying T2DM." (PMID 41109135, 2025).
preeclampsia (1 paper, 2022). Preeclampsia is a hypertensive disorder of pregnancy that is characterized by new-onset hypertension with proteinuria presenting after 20 weeks of gestation, and depending on mild or severe forms may initially present with severe headache, visual disturbances, and hyperreflexia. "Our results indicate that CDKN2A and TXNRD1 are highly expressed in STB-EVs derived from preeclampsia, further studies are needed to identify the impact of CDKN2A and TXNRD1 on ferroptosis pathway." (PMID 36343018, 2022). "In this study, we identified several central genes closely related to ferroptosis in STB-EVs (ALB, NOX4, CDKN2A, TXNRD1, and CAV1) that are potential biomarkers related to ferroptosis in preeclampsia." (PMID 36343018, 2022). "In this investigation, we demonstrated numerous key genes (ALB, NOX4, CDKN2A, TXNRD1, and CAV1) that are expected to act as biomarkers for ferroptosis in STB-EVs of preeclampsia." (PMID 36343018, 2022). "ALB, NOX4 and CAV1 are associate with the prosses of preeclampsia, and the other two genes (CDKN2A, TXNRD1) have not been linked directly to the occurrence of preeclampsia." (PMID 36343018, 2022).
presbycusis (1 paper, 2014). Bilateral hearing loss caused by progressive degeneration of cochlear structures and central auditory pathways, typically associated with the aging process. "The downregulation of Txnrd1 expression may have a special therapeutic significance for future efforts at prevention and/or treatment of presbycusis through gene therapy techniques." (PMID 24587312, 2014).
pulmonary fibrosis (1 paper, 2025). Chronic progressive interstitial lung disorder characterized by the replacement of the lung tissue by connective tissue, leading to progressive dyspnea, respiratory failure, or right heart failure. "TXN/TXNRD1 inhibitors not only have anti-tumor activity, but also inhibit pulmonary fibrosis by inhibiting NF-κB/TGF-β1/Smads pathway." (PMID 39744566, 2025).